E2F1 (E2F transcription factor 1)
Diseases named in the same sentence as E2F1 in open-access papers (continued):
Sharing a sentence is not in itself a finding about the gene and the disease.
breast carcinoma (continued). "Conversely, KDM2A was found to regulate E2F1-mediated gene transcription and thus to suppress the invasion and migration in breast cancer cells." (PMID 26430963, 2015). "Our group demonstrated that silencing E2F1 or E2F3 suppressed CA/CIN in Her2+ breast cancer, while their overexpression in mammary epithelial cells triggered CA/CIN that respectively correlated with decreases or increases in Nek2 protein levels." (PMID 26512919, 2015). "Recently Arf1 has been implicated in the control of cell proliferation, due to its ability to regulate pRB/E2F1 activity and gene expression enhancing proliferation and progression of breast cancer." (PMID 25754106, 2015). "Recently, mouse models demonstrated that the E2F activators are required in mammary tumor initiation, since ablation of E2F1 and E2F3 suppressed Her2/Neu and Myc-induced mammary tumorigenesis." (PMID 26512919, 2015). "On the other hand, let-7a inhibits the proliferation of human glioblastoma, human nonsmall cell lung tumor, Burkitt lymphoma, breast cancer cells, and primary fibroblasts, through the repression of Ras, c-myc, E2F1, and CDC34 as well as elevation of p21." (PMID 24165399, 2014). "Immunohistochemical analysis of 139 breast cancer tissue samples revealed a significant correlation between E2F1 and HOXB9 expression (p<0.001)." (PMID 25136922, 2014). "In breast carcinomas, E2F1 expression is correlated with proliferation and the poor survival of lymph node-positive breast cancer patients treated with fluorouracil, doxorubicin, and cyclophosphamide." (PMID 25136922, 2014). "For this experiment, nuclei extracts from T47D cells were used, since the concentration of E2F1 protein in the nuclei of T47D is higher than the other breast cancer cell lines." (PMID 25136922, 2014). "Survival analysis showed that E2F1 is a significant prognostic factor only among the HR(+)/HER2(−) breast cancer patients (Log-rank test; P = 0.027)." (PMID 25136922, 2014). "The TMCG/DIPY combination acted as an epigenetic treatment that reactivated RASSF1A expression and induced E2F1-mediated apoptosis in breast cancer cells." (PMID 25064027, 2014). "Recently, it has been suggested that ERα regulates E2F1 expression to mediate tamoxifen resistance in ERα-positive breast cancer cells." (PMID 25064027, 2014). "The induction of HOXB9 expression by E2F1 was observed by Q-PCR in several breast cancer cell lines overexpressing E2F1." (PMID 25136922, 2014). "In a study that aimed to predict the outcome in Korean women who underwent surgery for breast carcinoma, the E2F1-positive group had less tumor recurrences, lymph node metastasis during follow-up, and distant metastasis than the E2F1-negative group." (PMID 24023875, 2013). "To elucidate the role of eugenol-related down-regulation of E2F1 and its antiapoptosis target survivin in apoptosis induction in breast cancer cells, we studied the effect of E2F1 specific down-regulation on the cytotoxic effect of eugenol." (PMID 24330704, 2013). "In the present paper we present clear evidence that eugenol has potent anti-breast cancer properties both in vitro and in vivo with strong inhibitory effect on E2F1 and survivin." (PMID 24330704, 2013). "Quantitative real-time PCR arrays and MALDI-TOF mass spectrometry indicated that this combination (TMCG/DIPY) induced apoptosis in breast cancer cells by modulating the methylation levels of DNA and proteins (such as E2F1), respectively." (PMID 23251702, 2012). "As expected, the E2F1 index was related to chemotherapy response in the 3 large cohorts of breast cancer patients 3 tested previously (GSE21094, GSE25055, GSE25065)." (PMID 22578285, 2012).
breast carcinoma (continued). "We chose to begin with E2F1, as its transcript levels are reportedly prognostic in human breast cancer, and because the E2F1 protein stimulates tumor cell proliferation, a process that is inversely correlated with breast cancer patient survival." (PMID 21453498, 2011). "Upon nicotine-induced EGFR activation, Src, Akt and ERK1/2 were phosphorylated in MCF10 and MDA-MB-231 breast cancer cells, leading to the upregulation of E2F-1, Bcl-2 expression, and long-term cell survival." (PMID 22085699, 2011). "Using an algorithm we published recently, we found that the expression of KIAA0191 transcripts can be used in conjunction with those of E2F1 to more accurately predict breast cancer patient survival than does E2F1 expression alone." (PMID 21453498, 2011). "In breast cancer cells, P4 up-regulates the expression of E2F1 and hence indirectly affects transcription of classic E2F1 target genes." (PMID 21272326, 2011). "E2F1 increases the levels of endogenous EBP1 mRNA in breast carcinoma and other transformed cell lines." (PMID 21085677, 2010). "Regulation of the cell cycle including the modulation of Rb-E2F1 activity is the second major signaling pathway affected by lovastatin treatment in breast cancer cells." (PMID 20205716, 2010). "We have shown that in MCF-7 breast carcinoma cells, exogenous E2F1 expression increased EBP1 transcript levels." (PMID 21085677, 2010). "The gene expression of MCF-7 which has been exposed to lactic acidosis was depleted in gene sets representing E2F1 target genes, DNA replication, breast cancer poor prognosis, mitotic cycles and RNA processing." (PMID 20844768, 2010). "As expected, in parallel to the high levels of Hes-6, we identified a higher expression of E2F-1 in the breast cancer samples compared with that in the normal breast tissue samples, in agreement with what has been described by other researchers." (PMID 19891787, 2009). "We showed previously that Hes-1 represses the proliferation of breast cancer cells and that E2F-1 is directly inhibited by Hes-1 at the transcriptional level." (PMID 19891787, 2009). "The cell-cycle regulator E2F-1 was also significantly increased in breast cancer samples compared with normal breast tissue." (PMID 19891787, 2009). "In one report, E2F-1 protein correlated with Mib1/Ki67 expression and was expressed at higher levels in advanced-stage breast cancer." (PMID 19891787, 2009). "We earlier identified E2F-1 as a crucial transcription factor directly inhibited by Hes-1 at the transcriptional level in breast cancer." (PMID 19891787, 2009). "Further research with E2F-1 TFPs will continue to explore their therapeutic potentials and benefits in the field of breast cancer research." (PMID 18366791, 2008). "Other transcription factors with indirect effects in breast cancer were E2F1 and STAT5A, which are essential in the regulation of tumor growth and apoptosis." (PMID 18358079, 2008). "The efficient transduction of the E2F-1/TatHA peptides into breast cancer cells combined with their transcriptional effects on hTERT expression suggests an alternate route to inhibit telomerase expression in breast cancer cells." (PMID 18366791, 2008). "Under normal circumstances, E2F1 plays a role in stimulating growth through its regulation of the expression of genes required for cell cycle progression in breast cancer cells." (PMID 18431487, 2008). "This role is well documented in tumor cells, and particularly in breast cancer cells where E2F1 and its E2F1-target genes, including DHFR, PCNA and cyclin E, are overexpressed." (PMID 18431487, 2008).
breast carcinoma (continued). "Overall, these results suggest that transduction of E2F-1/TatHA fusion proteins in vitro is a moderately effective repressor of hTERT expression in the primary ductal breast cancer cell lines HCC1937 and HCC1599." (PMID 18366791, 2008). "Our analysis identified cis-regulatory motifs bound by ELK1, E2F1, NRF1 and NFY as principal motifs associated with breast cancer malignancy." (PMID 18823535, 2008). "Indeed, 40% of the STB tumors and 50% of the NKI tumors with low E2F1 expression levels belonged to nodal-positive patients at very low risk of metastases, reconfirming the impact of proliferation recently reported in a study evaluating breast cancer patients with 10 and more positive lymph nodes." (PMID 17535433, 2007). "E2F1 and other proliferation markers were measured by quantitative RT-PCR in 317 primary breast cancer patients from the Stiftung Tumorbank Basel." (PMID 17535433, 2007). "Assessment of E2F1 at the mRNA level in primary breast cancer is a strong determinant of breast cancer patient outcome." (PMID 17535433, 2007). "Breast cancer patients' outcome was comparably predictable by E2F1 levels, by the 70-gene signature, by the intrinsic subtype gene classification, by the wound response signature and by the recurrence score." (PMID 17535433, 2007). "Finally, multifactorial survival analysis revealed that lower expression levels of FTO-BTK/c-Myc-E2F1 significantly improved OS in breast cancer patients." (PMID 41281757, 2025). "Thus, our data suggest that the downregulation of c-Myc and E2F1 contributes to the suppression of malignancy in breast cancer cells by the combination of FB23 and ibrutinib." (PMID 41281757, 2025). "Consequently, BRD4 methylation affects the recruitment of the E2F1 TF to genes involved in mRNA translation in breast cancer cells." (PMID 40809945, 2025). "Moreover, the let-7 miRNA has been studied in breast cancer as strongly related to the induction of PR-B via activation of the E2 binding factor 1 (E2F1) promoter." (PMID 40305232, 2025). "Similarly, lower expression levels of FTO-BTK/E2F1 also significantly enhanced OS in breast cancer patients." (PMID 41281757, 2025). "In summary, our study revealed the stimulatory effects of XBP1s on cell proliferation, cell cycle progression from G1 to S phase, and the development of cross‐resistance to palbociclib and fulvestrant by modulating the SND1/E2F1 axis in HR+/HER2− breast cancer." (PMID 40940685, 2025). "To investigate whether c-Myc and E2F1 downregulation was involved in combination of FB23 and ibrutinib-suppressed breast cancer progression, we explored the effects of c-Myc and E2F1 overexpression (OE), both individually and in co-overexpression." (PMID 41281757, 2025). "In line with this, we investigated whether FTO and BTK influence OS in breast cancer patients through c-Myc and E2F1." (PMID 41281757, 2025). "Additionally, E2F1 enhanced DANCR transcription by directly binding to its promoter in breast cancer cells." (PMID 39119602, 2024). "While the roles of BIRC5 and E2F1 in drug resistance in HER2 breast cancer are understood, the involvement of USP1 and TRFC remains unclear." (PMID 38534787, 2024). "This could be the case of the miR17-92 cluster induced by AURKA, through E2F transcription factor 1 (E2F1) in breast cancer." (PMID 39598228, 2024). "In addition, we found that the E2F1 was recruited to the FOXM1 promoter region, indicating that CDCA5 was capable to affect FOXM1 expression via binding to E2F1, thereby promoting in the progression of breast cancer." (PMID 38978058, 2024). "E2F4, FOXM1, and E2F1 are all indicated in development and progression of breast cancer." (PMID 38886591, 2024). "Recent studies have found that E2F1 abnormally expresses in a variety of malignant tumors, such as breast cancer, prostate cancer, ovarian cancer, suggesting that it may be an important pathogenic factor in tumorigenesis and development." (PMID 37198697, 2023).
breast carcinoma (continued). "E2F1 drives breast cancer metastasis by upregulating the FGF13 gene and altering cell migration." (PMID 36833320, 2023). "E2F1, a member of E2F transcription factor family, was up-regulated and confirmed as an oncogene in multiple human cancers, including hepatocellular cancer, breast cancer and gastric cancer." (PMID 37601683, 2023). "Therefore, LINC00511/miR-185-3p/E2F1/Nanog axis has been identified as an important route for induction of stemness and tumorigenesis in breast cancer." (PMID 37124625, 2023). "Similarly, upregulation of E2F1 expression in 4T1 breast cancer cells following static magnetic field treatment has been observed to downregulate hTERT expression and reduce telomerase activity." (PMID 37612721, 2023). "Additionally, it was shown that E2F1 was up-regulated and active in the carcinogenesis of breast cancer, contributing to the creation of Nanog in this disease." (PMID 38012557, 2023). "Therefore, PCK2 promotes cell proliferation and cell cycle progression by regulating mTORC1 and E2F1 in ER+ breast cancer." (PMID 35757841, 2023). "Furthermore, they demonstrated that overexpression of SEC61G contributes to the development and metastasis of breast cancer by modulating glycolysis, a process regulated by the transcription factor E2F1." (PMID 37878007, 2023). "Consequently, enhanced binding of E2F1 to the hTERT promoter leads to the inhibition of hTERT transcription in breast cancer cells." (PMID 37612721, 2023). "Estrogen might exert its physiological functions through lncRNAs, such as ERINA, an estrogen-responsive lncRNA, which promotes breast cancer development through the E2F1/RB1 pathway." (PMID 35685427, 2022). "E2F1 promotes tumor cell viability, metastasis, and cell cycle in breast cancer cells." (PMID 35293275, 2022). "This study aimed to determine the role of RPL5/E2F transcription factor 1 (E2F1) in breast cancer." (PMID 35293275, 2022). "Moreover, two independent studies demonstrated that E2F1 transcriptionally regulates the expression of FOXM1 in MCF7 breast cancer cells, opposite the direction of transcriptional regulation shown in our study." (PMID 35835838, 2022). "Concordant with our findings, LINC00511 was shown to accelerate the G1/S shift and prevent apoptosis in ER-negative breast cancer, and manipulation of LINC00511 expression confirmed a role in tumorigenesis and stemness through miR-185-3p/E2F1/Nanog axis in breast cancer." (PMID 35893227, 2022). "This study revealed that E2F1 is weakly expressed in breast cancer tissues." (PMID 35293275, 2022). "We found that RPL5 regulated ERS and autophagy of breast cancer cells via regulating E2F1." (PMID 35293275, 2022). "RPL5 was downregulated and E2F1 was upregulated in breast cancer." (PMID 35293275, 2022). "Having observed direct targeting of E2F1 by miR-183-5p|+2 in an in vitro setup, we hypothesized that the expression and activity of E2F1 should be inversely correlated with the expression of miR-183-5p|+2 in breast cancer patients." (PMID 35655310, 2022). "Also, it has been reported that the cancer-promoting effect of miR-361-3p with abnormally elevated expression in breast cancer tissue is achieved by inhibiting the E2F1/P73 pathway." (PMID 36590309, 2022). "To date, E2F1-targeting treatment has been used in chemotherapy for colorectal and breast cancers." (PMID 34726120, 2021). "al indicated low expression of E2F1 as a marker of favorable breast cancer outcome." (PMID 33852600, 2021). "This was recapitulated in human HER2+ breast cancers after separation into E2F1 high/low quartiles." (PMID 33947907, 2021). "Here we revealed the oncogenic role of E2F1 in breast cancer via enhancing SEC61G expression." (PMID 34039955, 2021).
breast carcinoma (continued). "Recently, it has been identified that PIR positively regulates breast cancer cell proliferation, xenograft tumor formation, and metastasis, through an enforced transition of G1/S phase of the cell cycle by upregulation of E2F1 expression at the transcriptional level." (PMID 34262943, 2021). "Moreover, enforced E2F1 expression also increased the endogenous ESRP1 expression in breast cancer cell lines." (PMID 34362878, 2021). "In addition, the Kaplan–Meier survival analysis using the TCGA database revealed that breast cancer patients expressing high levels of E2F1 exhibit a poor prognosis, which is in harmony with ESRP1." (PMID 34362878, 2021). "Low E2F1 gene expression is predictive of metastasis-free survival in breast cancer patients." (PMID 34179840, 2021). "While mutations in E2F1 are not common in human breast cancer, mutations within the E2F pathway occur in over 25% of breast cancer patients, illustrating the importance of the pathway." (PMID 33947907, 2021). "By analyzing gene signatures in The Cancer Genome Atlas, it was identified that increased E2F Transcription Factor 1 (E2F1) and increased E2F Transcription Factor 2 (E2F2), two members of the E2F family, were correlated with a loss of function of Rb in ER+ breast cancers." (PMID 34830174, 2021). "Based on these recent evidence, the aim of this study was to investigate the frequency of CNV of E2F1 in 222 Italian women with breast cancer in order to better elucidate the contribution of this structural variant as a potential predisposing factor to breast carcinogenesis." (PMID 33691613, 2021). "Furthermore, the functional relevance of E2F1 upregulation in oxygen-deprived breast cancer cells is explicated by the finding that E2F1 alters the cancer spliceome by upregulating splicing factor SRSF7 under hypoxia." (PMID 34362878, 2021). "Furthermore, E2F1 skews the cancer spliceome by upregulating splicing factor SRSF7 in hypoxic breast cancer cells." (PMID 34362878, 2021). "Since anomalies in expression or in number of copies of E2F1 have been related to several cancers, we aimed to study number of germline copies of E2F1 in women with breast cancer in order to better elucidate their contribution as predisposing factor to this tumour." (PMID 33691613, 2021). "Additionally, we found that altered E2F1 copies were present prevalently in the patients with contralateral breast cancer (20%) and all of them had a positive family history, both typically associated with hereditary cancer." (PMID 33691613, 2021). "Interestingly, in a mouse model of metastatic breast cancer, the lung colonization capacity of CTCs and the numbers of metastatic lesions in the lung were strikingly reduced in mice on both the E2F1 and E2F2 knockout backgrounds." (PMID 34476219, 2021). "Indeed, E2F2/5/8 have been shown to be novel biomarkers for prognosis for ovarian cancer, E2F1/2/5/8 for lung cancer, and multiple members of E2F for gastric and breast cancer." (PMID 33329696, 2020). "Besides its influence on estrogen receptor signaling, RIP140 represses transactivation of E2F1 and inhibits expression of several E2F1 target genes in breast cancer cell lines." (PMID 32157438, 2020). "We also found that CSNK2β reduces the expression of E2F1, which might affect a large fraction of genes in breast cancer." (PMID 33013272, 2020). "MiR-302b by regulating E2F1/ATM axis could enhance breast cancer cell sensitivity to cisplatin and promote G1/S arrest in BC cells." (PMID 33330110, 2020). "A survey of promoter binding sequences disclosed that all genes in the amplicon possess several putative binding sequences in their promoters for ERα, ERβ and the transcription factor E2F1 which is a target of activation by the cyclin D/CDK4 cascade in breast cancer with high proliferation fraction." (PMID 32987805, 2020).